ERP44 (endoplasmic reticulum protein 44)
Description:
Mediates thiol-dependent retention in the early secretory pathway, forming mixed disulfides with substrate proteins through its conserved CRFS motif. Inhibits the calcium channel activity of ITPR1. May have a role in the control of oxidative protein folding in the endoplasmic reticulum. Required to retain ERO1A and ERO1B in the endoplasmic reticulum.
Synonyms: KIAA0573; TXNDC4; PDIA10
Tractability: Small molecule: a structure with a bound ligand is known. Antibody: its Gene Ontology location is reachable by antibodies, with high confidence; UniProt predicts a signal peptide or a membrane-spanning region. PROTAC: ubiquitination databases record sites on it; its protein half-life has been measured.
Gene: Protein-coding gene on chromosome 9 (99,979,185 to 100,099,052, reverse strand). Ensembl gene ENSG00000023318.
Subcellular location: Endoplasmic reticulum lumen
Pathways (Reactome):
Immune System: Neutrophil degranulation
Gene Ontology:
Molecular function: protein binding; protein disulfide isomerase activity
Biological process: glycoprotein metabolic process; protein folding; response to endoplasmic reticulum stress; response to unfolded protein; cell redox homeostasis
Cellular component: cell surface; endoplasmic reticulum lumen; endoplasmic reticulum membrane; endoplasmic reticulum-Golgi intermediate compartment; extracellular exosome; extracellular region; specific granule lumen
Genetic constraint (gnomAD): Loss-of-function variants: 8 observed, 17.68 expected, observed/expected ratio (o/e) 0.45, 90% interval 0.26 to 0.82. The upper end of that interval is the gene's LOEUF score, 0.82, which puts it in group 3 of 6, group 1 being the genes least tolerant of losing a copy. Missense variants: 131 observed, 194.04 expected, observed/expected ratio (o/e) 0.68, 90% interval 0.58 to 0.78. Synonymous variants: 50 observed, 65.99 expected, observed/expected ratio (o/e) 0.76, 90% interval 0.6 to 0.96.
Homologues: Orthologues: chimpanzee ERP44 (100% identical), macaque ERP44 (99% identical), dog ERP44 (96% identical), guinea pig ERP44 (95% identical), rabbit ERP44 (95% identical), mouse Erp44 (93% identical), rat Erp44 (93% identical), pig ERP44 (82% identical), tropical clawed frog erp44 (79% identical), zebrafish erp44 (78% identical), Drosophila melanogaster ERp44 (48% identical), Caenorhabditis elegans erp-44.1 (44% identical), and 1 more. Paralogues in human: PDIA4 (22% identical), P4HB (21% identical), PDIA2 (20% identical), PDIA3 (20% identical), PDILT (19% identical), TXNDC5 (19% identical), TMX3 (16% identical), PDIA5 (16% identical), TXNDC11 (15% identical), PDIA6 (14% identical), ERP27 (9% identical), TMX1 (9% identical), and 1 more.
Diseases named in the same sentence as ERP44 in open-access papers:
ERP44 is named in the same sentence as 29 diseases in open-access papers, as found by Europe PMC text mining. Sharing a sentence is not in itself a finding about the gene and the disease. The quoted sentences say what the papers report.
nasopharyngeal carcinoma (9 papers, 2021 to 2025). A carcinoma arising from the nasopharyngeal epithelium. "Previous studies in HNSC have implicated ERP44 in tumor progression; ERp44, secreted via exosomes from ER-stressed nasopharyngeal carcinoma cells, is a key contributor to chemoresistance in nasopharyngeal carcinoma." (PMID 41049606, 2025). "Another study found that in nasopharyngeal carcinoma, ER stress induces the secretion of exosomes containing ER protein 44 (ERP44), which transmit chemotherapy resistance to neighboring cells." (PMID 41209558, 2025). "Another similar study indicated that exosomal endoplasmic reticulum resident protein 44 (ERp44) derived from endoplasmic reticulum-stressed cells promotes cisplatin resistance in nasopharyngeal carcinoma, thereby mediating cell apoptosis and pyroptosis." (PMID 38216595, 2024). "When exposed to ER stress, nasopharyngeal carcinoma cells secrete endoplasmic reticulum resident protein 44(ERp44)-containing exosomes, which boost the chemoresistance of neighboring cells." (PMID 36890838, 2023). "ERP44 promotes progression in nasopharyngeal carcinoma via its interaction with ATP citrate lyase and regulation of epithelial-mesenchymal transition (EMT)." (PMID 35707371, 2022). "In nasopharyngeal carcinoma, the interaction between ERP44 and ACLY promotes the malignant phenotype of nasopharyngeal carcinoma cells." (PMID 36059811, 2022).
colorectal cancer (3 papers, 2020 to 2025). A primary or metastatic malignant neoplasm that affects the colon or rectum. "Most recently ERp44, an ER resident protein involved in protein folding, has been shown to be a target for auto-antibodies in colorectal cancer patients and was proposed as a biomarker." (PMID 33019700, 2020). "Moreover, ERP44 protein was abundant in colorectal cancer(CRC) tissues and could act as a prognostic biomarker." (PMID 33593371, 2021). "For instance, Prosaposin (PSAP), Endoplasmic reticulum resident protein 44 (ERP44), Proteasome subunit alpha type-6 (PSMA6), and Histone H4 (HIS1H4A) were highly expressed in most of the breast and colorectal cancer samples." (PMID 41516087, 2025).
glioma (3 papers, 2020 to 2025). A benign or malignant brain and spinal cord tumor that arises from glial cells (astrocytes, oligodendrocytes, ependymal cells). "Beyond HNSC, ERP44 dysregulation has been documented in diverse malignancies including gastric cancer, lung cancer, and gliomas, where it influences proliferation, apoptosis resistance, and endoplasmic reticulum stress." (PMID 41049606, 2025).
Insulin resistance (3 papers, 2011 to 2025). Increased resistance towards insulin, that is, diminished effectiveness of insulin in reducing blood glucose levels. "In adipocyte-specific Ubc9 deficient mice fed a high-fat diet exhibiting obesity, insulin resistance, and hepatosteatosis, the deficiency of Ubc9 results in the loss of ERp44 SUMOylation at lysine 76 (K76) in the thioredoxin-like domain." (PMID 41333024, 2025). "It is unclear at the present if decreased levels of ERp44 and DsbA-L associated with obesity and insulin resistance represent particular manifestations of overall dysfunction in the ER compartment." (PMID 21600065, 2011). "Decreased production of total and HMW adiponectin associated with insulin resistance may be due in part to decreased cellular levels of ERp44 and DsbA-L." (PMID 21600065, 2011). "The covalent binding between ERp44 and ERO1α may be controlled by modulating ERp44 SUMOylation in adipocytes which provides a viable strategy for addressing obesity and insulin resistance." (PMID 41333024, 2025).
Obesity (3 papers, 2011 to 2025). Accumulation of substantial excess body fat. "It is possible that obesity-related decrease in HMW adiponectin production is in part due to ER stress independent of changes in ERp44 or DsbA-L." (PMID 21600065, 2011).
Hypertension (2 papers, 2020 to 2023). The presence of chronic increased pressure in the systemic arterial system. "We speculate these data suggest that dysregulation of placental expression of ERp44 contributes to the hypertension which is characteristic of PE." (PMID 36848863, 2023). "The lower placental zinc may contribute to dysfunction of the ERp44/ERAP1 complex, exacerbating the hypertension in PE." (PMID 36848863, 2023). "Therefore, the lower placental zinc concentration may also contribute to the dysfunction of the ERp44/ERAP1 complex, further exacerbating the hypertension in PE." (PMID 36848863, 2023). "Therefore, we speculate that in PE, the higher ERp44 forms a complex with ERAP1, preventing the secretion and cleavage of Ang II, which would otherwise promote hypertension." (PMID 32210971, 2020).
oral squamous cell carcinoma (2 papers, 2022 to 2025). "More importantly, honokiol can promote the apoptosis of oral squamous cell carcinoma cells and exert anti-cancer effects by inhibiting the expression of ERP44 in oral squamous cell carcinoma cells." (PMID 36059811, 2022). "Treatment of oral squamous cell carcinoma (OSCC) cell lines, HN-22 and HSC-4, with honokiol caused degradation of ERp44 in a dose- and time-dependent manner without affecting ERp44 mRNA expression." (PMID 40867591, 2025).
preeclampsia (2 papers, 2021 to 2025). Preeclampsia is a hypertensive disorder of pregnancy that is characterized by new-onset hypertension with proteinuria presenting after 20 weeks of gestation, and depending on mild or severe forms may initially present with severe headache, visual disturbances, and hyperreflexia. "Additionally, research has shown that miR-101 is inversely correlated with ERp44 in preeclampsia placentas, and its upregulation in vitro can inhibit apoptosis in trophoblast cells by targeting ERp44, suggesting a protective role against ER stress-induced apoptosis." (PMID 40075783, 2025).
adenovirus infection (1 paper, 2016). "With the adenovirus infection approach ERP44 was highly expressed in ER of A549 cells." (PMID 27347718, 2016). "Due to the low efficiency of the transient transfection of pCMV-ERP44-IRES-DsRed2 in A549 cells (<5%), adenovirus infection was used to over-express ERP44 in the cells." (PMID 27347718, 2016).
breast carcinoma (1 paper, 2021). "In breast cancer, ERp44 was elevated in mammospheres and played key roles in anchorage-independent cell proliferation." (PMID 33593371, 2021). "In breast cancer, ERp44 played an important role in anchorage-independent cell proliferation." (PMID 33593371, 2021).
dysplasia (1 paper, 2022). A usually neoplastic transformation of the cell, associated with altered architectural tissue patterns. "Adversely, ERp44 KO directly results in the decreased extracellular VEGF, which impairs the EndMT and is responsible for the dysplasia EC." (PMID 35088919, 2022).
heart failure (1 paper, 2023). Inability of the heart to pump blood at an adequate rate to meet tissue metabolic requirements. "It is possible that ZnT5-KO inhibits the function of ERp44 and allows aberrant secretion of male-specific ERp44-client proteins, leading to the heart failure." (PMID 37160917, 2023).
lung adenocarcinoma (1 paper, 2016). A carcinoma that arises from the lung and is characterized by the presence of malignant glandular epithelial cells. "In this study, we used the human lung adenocarcinoma A549 cell line to examine the role of endoplasmic reticulum protein 44 (ERP44), which has been reported to regulate calcium release inside of the endoplasmic reticulum (ER), in cell migration." (PMID 27347718, 2016).
myeloma (1 paper, 2013). "To confirm that endogenous ERp44 and Prx4 interact in physiological conditions, we analyzed Ig-λ producing J558L murine myeloma cells or a transfectant secreting IgM (J[μs])." (PMID 23979138, 2013).
neuroblastoma (1 paper, 2016). Neuroblastoma (NB) is the most common solid, extracranial childhood tumor. "Moreover, the overexpression of ERP44 did not affect the migration of the human neuroblastoma cell line SH-SY5Y, which mainly expresses IP3R1." (PMID 27347718, 2016).
oral cancer (1 paper, 2025). "Depletion of ERp44 markedly impaired oral cancer cell proliferation and colony formation." (PMID 41049606, 2025).
renal carcinoma (1 paper, 2020). A carcinoma arising from the epithelium of the renal parenchyma or the renal pelvis. "In renal cancer cells, ER stress was shown to be induced by nelfinavir, as evidenced by the increase in GRP78, endoplasmic reticulum resident protein 44 (ERp44), and endoplasmic oxidoreductin-1-like protein α (ERO1-Lα)." (PMID 33228205, 2020).
tumor (12 papers, 2014 to 2025). "ERP44 was notably overexpressed in tumor tissues and associated with key oncogenic pathways and immune cell infiltration patterns." (PMID 41049606, 2025). "ERP44 expression is significantly higher in tumor tissues compared to normal tissues in several cancers, including GBM, HNSC, KICH, KIRP, PRAD, and UCEC (p < 0.05)." (PMID 41049606, 2025). "Protein expression analysis using the HNSC-CPTAC dataset further corroborated these findings, showing significantly elevated protein levels of ERP44 in tumor tissues compared to normal tissues, as determined by a Wilcoxon rank sum test (p < 0.001)." (PMID 41049606, 2025). "Honokiol applied to OSCC cell lines HN22 and HSC4 decreased the expression of the enzyme nitric oxide synthase (iNOS) and the level of the ERp44 ER-resident protein and inhibited the proliferation of tumour cells and colony formation." (PMID 40943669, 2025). "Gene expression analysis demonstrated that ERP44 expression levels were significantly higher in tumor tissues compared to normal tissues within the TCGA-HNSC dataset (p < 0.001)." (PMID 41049606, 2025). "Erp44 plays an important role in tumor development, not only in promoting cell proliferation and migration, but also in reducing cisplatin sensitivity by activating nuclear factor kappa B (NF-κB) to inhibit cell apoptosis." (PMID 36032078, 2022). "Moreover, ERP44 and histone H4 family members are reported to be broadly expressed across multiple tumor types, supporting their potential relevance as cross-tissue markers." (PMID 41516087, 2025). "This suggests that ERP44-overexpressing tumor cells might possess enhanced survival mechanisms that bypass mTOR dependence, potentially related to its roles in ER stress adaptation or calcium signaling." (PMID 41049606, 2025). "Thus, under ER stress, tumor cells produced EVs containing Erp44, which migrated to neighboring cells, enhanced chemotherapeutic resistance, and promoted the proliferation of CNE2 cells." (PMID 36032078, 2022). "As expected, when ERp44 was downregulated, tumor growth was inhibited." (PMID 33593371, 2021). "Studies have reported the abnormal expression of ERp44 in tumor." (PMID 33593371, 2021). "With the diverse function of ERp44, it also influences tumor progression." (PMID 33593371, 2021). "It is interesting to note that ERp44 was consistently identified in all tissues and samples tested by both MGL- and VVA–LWAC, despite its weak staining on tumor tissue sections, and further studies are warranted to investigate the role of ERp44 in EOC." (PMID 33019700, 2020). "Additionally, it limited inflammation and tumour growth in BALB/c mice with HN22 cell xenografts and initiated apoptosis through suppressing the in vitro and in vivo expression of iNOS/NO and ERp44 in the HSC4 and HN22cells and xenograft tumours." (PMID 40943669, 2025). "Compared to tumor tissues from animals that received no treatment or LOFU or 17AAG alone, immunoblot analysis demonstrated a significant increase in the expression of ERp78 (p<0.03), ERp44 (p<0.05), and ERp57 (p<0.04) protein levels in tumor tissues following combination treatment with LOFU+17AAG." (PMID 25594042, 2014).
cancer (5 papers, 2016 to 2025). A tumor composed of atypical neoplastic, often pleomorphic cells that invade other tissues. "AGR2 and ERp44 loss-of-function experiments partially mimicked the effects of DDAs on cancer cells, and DDAs were found to disrupt disulfide-mediated AGR2 dimerization, as well as disulfide bonding between ERp44 or PDIA1 and their client proteins." (PMID 40867591, 2025). "Collectively, these results underscore ERP44’s pan-cancer oncogenic role, where its overexpression correlates with poor survival across diverse malignancies." (PMID 41049606, 2025). "For instance, significant positive correlations are noted between ERP44 and activated dendritic cells (aDC) in several cancer types such as BLCA, BRCA, HNSC, and LGG, indicating a potential role in promoting immune response." (PMID 41049606, 2025). "ERP44, an endoplasmic reticulum resident protein involved in disulfide bond formation and calcium homeostasis, has garnered increasing attention in cancer research." (PMID 41049606, 2025). "The assessment of chemotherapeutic drug sensitivity in relation to ERP44 expression has provided compelling evidence for its predictive value, shedding light on the intricate relationship between this protein and the efficacy of various cancer treatments." (PMID 41049606, 2025). "Based on this effect of ERP44 on Ca2+, we speculate that ERP44 is involved in cancer cell migration." (PMID 27347718, 2016). "A second-generation biotinylated DDA identified the PDIs ERp44, PDIA1, and AGR2 as the major DDA targets in cancer cells." (PMID 40867591, 2025). "Why ERp44, AGR2, or AGR3 are essential for specific cancer cell lines is unclear but may relate to their unique biological and biochemical functions." (PMID 40867591, 2025). "Here, we provide a review of the literature relating to the non-canonical PDIs ERp44, AGR2, and AGR3, which have been identified as strong dependencies in specific cancer subtypes according to the DepMap database." (PMID 40867591, 2025).
metabolic disorders (2 papers, 2021 to 2025). "The loss of SUMOylation at lysine 76 of endoplasmic reticulum protein 44 (ERP44) enhances its degradation and disrupts binding to endoplasmic reticulum oxidoreductase 1 alpha (ERO1A), protecting mice from HFD-induced metabolic disorders." (PMID 40729009, 2025).
infection (1 paper, 2020). The state of being infected such as from the introduction of a foreign agent such as serum, vaccine, antigenic substance or organism. "The female mice exhibited higher expression levels of AKT1, BTK, CCL9, and LSP1 (KO, 1A0), PPARG (KO, 1A0, and 6A2), CFLAR, and ERP44 (1A0, 6A4), CCL9 (KO, 1A0, and 6A4), RCC2, and RELA (KO), KAT2B (6A2) and FKBP5 (1A0, 6A2, and 6A4) compared to males in response to infection." (PMID 32670284, 2020). "However, in response to infection, male mice exhibited higher expression levels of CFLAR, and FKBP5 (KO, 1A3), AKT1, and CCL9 (1A3, 6A2), C1QC (6A2), LSP1 (1A3, 6A2, and 6A4), CKAP2, and KAT2B (KO), TACC2 (1A0), RCC2 (1A3, 6A2), PPARG (1A3, 6A4), and ERP44 (6A2) compared to females." (PMID 32670284, 2020).
ERP44 also shares sentences with these, for which no sentence is quoted: lung carcinoma (2 papers); cardiac hypertrophy (1); diabetic (1); gastric cancer (1); hepatocellular carcinoma (1); melanoma (1); ovarian carcinoma (1); Sepsis (1).